CCR2 (C-C motif chemokine receptor 2)
Diseases named in the same sentence as CCR2 in open-access papers (continued):
Sharing a sentence is not in itself a finding about the gene and the disease.
cancer (continued). "CCL2/CCR2 signaling was demonstrated to play crucial roles in the metastatic process, stimulating cancer cell proliferation, invasion and migration, and promoting metastatic outgrowth and colonization." (PMID 26885690, 2016). "Plenty of researches suggest that CCL2/CCR2 is related to poor outcome and metastatic events in several cancers." (PMID 26701209, 2016). "Cell lines derived from MMTV-neu carcinomas in wild type and Ccr2-/- backgrounds secrete CCL2 in culture." (PMID 27820834, 2016). "In monocytes, an increase in CXCR4 expression has been shown in CD14+CD16− cells cultured with cancer cells, alongside increases in the expression of CCR2, CXCR1 and CXCR2." (PMID 25251539, 2014). "This chemokine, produced by CAFs, was reported to confer invasive and CSC phenotypes on carcinoma cells by acting directly through CCR2 and CCR4 receptors." (PMID 24216702, 2013). "For this purpose we elaborated a chimera system in which a Luciferase trafected CCR2+ cancer cell line (TRAMP-C1) is implanted into CCR2−/− mice that were then reconstituted with BM cells from CCR2+ immunocompetent mice." (PMID 22279523, 2012). "The current study focuses on differentiating the contribution of CCL2-CCR2 interaction within CCR2+ BM-derived CD11b+Gr1+ cells from the autocrine effect of CCL2 on CCR2 expressed by the cancer cells." (PMID 22279523, 2012). "As an alternative, antagonizing CCR2 was suggested as an approach with wider applicability for cancer therapy." (PMID 21943176, 2011). "However, this increase was significantly diminished when cancer cells were cocultured with CCR2‐ or PPARα‐silenced ADSCs." (PMID 41160815, 2026). "Furthermore, bidirectional signaling between macrophages and cancer cells involving CCR2 and CX3CR1 has been identified as a key mechanism driving lung cancer progression, highlighting the broader immunological relevance of this axis beyond T cell activity." (PMID 41149503, 2025). "Given the major role of CCL2 in immunosuppressive processes, combinatorial approaches involving ion channel modulators and CCR2 antagonists or immune checkpoint inhibitors may yield synergistic benefits in cancer treatment." (PMID 40806751, 2025). "The upregulation of CCL2/CCR2 is vital for the monocyte recruitment to transform into macrophages that can be transformed into M2 polarized macrophages for impairing CD8+ T cell-induced anti-cancer immune responses." (PMID 38997297, 2024). "Therefore, the conclusions regarding markers for survival, mortality, and quality of life apply to all cancers being treated with anti-PD-1 in combination with a CCR2 antagonist." (PMID 39185154, 2024). "Notably, rapamycin treatment not only downregulated CCR2 protein expression but also restricted the migration of TEMs toward cancer cells, suggesting the potential involvement of mTORC1 signaling in CCR2-mediated macrophage migration." (PMID 38409249, 2024). "Strategies to target CCL2/CCR2 axis as cancer therapy are under investigation." (PMID 39199652, 2024). "In addition to BMS-813160 and PF-04136309, several other CCR2 inhibitors have shown promising potential in cancer therapy." (PMID 39286635, 2024). "To confirm whether or not the CCR2i had a direct suppressive effect on CCR2‐positive cancer cells other than its antiangiogenic effect, we examined the CCR2 expression in the first serous PDX using IHC." (PMID 36810973, 2023). "Also increased by HFD but less so by the cancer cells was Ccl2 in contrast to its receptor Ccr2 that was modestly increased by the HFD but highly upregulated in the cancer groups." (PMID 38264656, 2023). "Third, overcoming resistance to antiangiogenic cancer therapy via CCR2 inhibition is expected." (PMID 36810973, 2023). "The functional differences between CCR2 isoforms in human cancer cells and details of the change in downstream signal pathways by CCR2i remain unclear." (PMID 36810973, 2023).
cancer (continued). "While the importance of CCL2/CCR2 signaling in macrophages during cancer progression is well documented, HtrA2 may regulate macrophage recruitment." (PMID 36704205, 2023). "The interaction between CCL2 and CCR2 is essential for macrophage-related functions in cancer progression, such as mediating cancer-related inflammation, regulating the balance between M1 and M2 macrophages, facilitating the recruitment of TAMs, and providing anti-apoptotic signals." (PMID 37628994, 2023). "US clinical trials using Repurposed angiotensin receptor antagonists for CCR2 inhibition in cancer." (PMID 37114134, 2023). "Furthermore, CCR2 is expressed in various human cancers, including skin, head and neck, glioma, and uterine cervical cancer." (PMID 36810973, 2023). "Importantly, upregulation of CCR2 and its ligand CCL2 has also been found in PCa and associated with cancer advancement, metastasis, and relapse, and upregulation of CCL18 has been shown to correlate with malignant progression of PCa." (PMID 36321189, 2023). "CCR2 is among the most extensively studied chemokine receptors, with reports describing roles in various inflammatory diseases, ranging from infection and atherosclerosis to cancer." (PMID 35551672, 2022). "In addition, the CCL2/CCR2 axis can promote cell survival by inhibiting autophagic death and apoptosis of cancer cells by activating the phosphatidylinositol 3-kinase (PI3K)/AKT/mammalian target of rapamycin (mTOR)-dependent pathway." (PMID 35281057, 2022). "However, this maturation is blocked under the presence of abundant HCC cells and in this case CCR2+ myeloid cells promote cancer progression by suppressing NK cells." (PMID 35674109, 2022). "MCP-1 and CCR2 may play pivotal roles in cancer progression by recruiting macrophages into cancer tissue." (PMID 35551672, 2022). "In recent years, the role of the chemokine CCL2 and its major receptor CCR2 in cancer pathogenesis has received special attention, and elevated levels of CCL2 have been associated with increased growth and progression of a variety of cancers." (PMID 35957694, 2022). "A CCR2 antagonist, 747, enhances the anti-cancer efficacy of sorafenib by blocking TAMs." (PMID 36071839, 2022). "Chemokines (CCR1, CCR2, CCR3, CCR4, CCR5, CCR6, CCR7, and CCR8) and receptor genes (CXCL1-17, CCL1-14, CCL16-26) were positively associated with necroptosis levels in various cancers." (PMID 36170029, 2022). "Interestingly, in regorafenib-resistant cancer cells, β-catenin was found to be a direct transcriptional activator of CCR2 expression." (PMID 36445121, 2022). "In addition, immunohistochemistry was used to confirm that the expression of C1QC and CCR2 in tissues of the three cancer models with Apoe-/- mice were significantly decreased." (PMID 36147474, 2022). "CCR2 was described to be expressed on many cell types, such as immune and cancer cells." (PMID 36429101, 2022). "Recent studies have suggested that CCR2–MCP-1 signaling may promote cancer progression due to their overexpression in cancer cells." (PMID 35551672, 2022). "CCR2 upregulation is closely related to the recurrence and metastasis of advanced cancers." (PMID 34464477, 2021). "CCR2 is the chemokine mediating its biological effects through the G protein signaling pathway, expressed in various cells, consisting of monocytes, dendritic cells (DCs), endothelial cells, and cancer cells." (PMID 33949150, 2021). "Furthermore, a clinical study (NCT03767582) of a drug (BMS-813160) that is expected to suppress the mobilization of TAMs in cancer tissues by suppressing both CCR2 and CCR5 is also in progress." (PMID 34445235, 2021). "Further understanding the correlation of CCR2 expression and TICs regulation could provide novel insight for treatment of cancer." (PMID 34251980, 2021).
cancer (continued). "Furthermore, in the vast majority of solid cancer models, M2-like Mφs and/or TAMs at the cancer site differentiate in situ from circulating CCR2+CD14++CD16– classical monocytes, recruited via cancer cell-secreted CCL2." (PMID 34249942, 2021). "Expression of CCR2 by cancer cells is rather widespread, although the levels of expression may be extremely heterogenous." (PMID 34804061, 2021). "It seems that CCR2+ macrophages have essential roles in inflammation, cancer, and fibrosis." (PMID 33614685, 2021). "All these data suggest that the CCL2/CCR2 axis could be a promising target for cancer treatment and prevention." (PMID 34356595, 2021). "As illustrated above, the signaling axis of CCL2/CCR2 in monocytes/macrophages and T cells has a great impact on cancer immunity, and accumulating evidence also supports the concept that cancerous cells can directly employ CCR2 to promote survival/growth and metastasis." (PMID 34804061, 2021). "CCR2+ cancer cell invasiveness was enhanced by fibroblast-derived CCL2 via SRC and PKC activation." (PMID 34386431, 2021). "Propagermanium, a CCR2 antagonist which is currently administered clinically for the treatment of individuals with a hepatitis B virus infection, was shown to have a marked inhibitory effect on cancer metastasis." (PMID 35006432, 2021). "Furthermore, changes in CCR2 expression were noted in cardiac and pulmonary disorder models and, to some extent, in cancer models such as adenocarcinoma." (PMID 34500609, 2021). "The development of CCR2 inhibitors has also yielded encouraging results in cancer treatments." (PMID 33463063, 2021). "Although CCR2+ Treg accumulated in various cancers, it could be depleted by low‐dose cyclophosphamide, which allowed the definition of a novel target for improving chemotherapic efficacy." (PMID 34464477, 2021). "CCR2-/- cancer cells were also more sensitive to CTL-mediated killing, compared to WT cancer cells." (PMID 34804061, 2021). "Besides monocytes, CCR2 expresses dendritic cells (DCs), NK cells, MDSCs, and cancer cells; the CCL2-CCR2 pathway is also a major player in chemokine signaling in the TME." (PMID 34445235, 2021). "As we highlighted above some aspects of how to target CCL2/CCR2 in cancer, we also contend that combination therapy may broaden and improve application of CCR2 antagonism as cancer therapy." (PMID 34804061, 2021). "Together, it may be important to consider the role of CCR2 in regulating traffic and function of Tregs when targeting CCR2 in cancer therapy." (PMID 34804061, 2021). "The CCL2/CCR2 axis may represent a unique opportunity for anti-cancer therapy and work in this area is already being explored." (PMID 34353349, 2021). "Moreover, experimental studies using xenotransplanted tumors have revealed the involvement of the CCL2/CCR2 axis in cancer metastasis." (PMID 33330033, 2020). "In addition, increased CCL2 production by splenic myeloid cells and stromal cells in cancer appears to contribute to the accumulation of myeloid progenitors, which upregulate their CCR2 expression in the spleen." (PMID 33042791, 2020). "In addition to the differentiation into CAF, MSC also allow TAM to migrate into the cancer environment via C-C chemokine receptor type 2 (CCR2)." (PMID 32987868, 2020). "The increasing number of studies indicate that neutralization of CCL2, acting via CCR2, might be effective in attenuating neuropathic pain and cancer pain." (PMID 33408720, 2020). "Inhibition of CCL2/CCR2 has been explored in the clinical setting as a possible cancer therapeutic." (PMID 33247183, 2020). "Interestingly, the results identified CC chemokine receptor 2 (CCR2) as a top upregulated gene in regorafenib-resistant (regR) cancer cells." (PMID 31501414, 2019). "Among the many chemokines associated with cancer progression, CCL2/CCR2 signaling may be considered a major player in promoting tumorigenesis and metastasis." (PMID 30871117, 2019).
cancer (continued). "However, the mechanisms through which CCL2/CCR2 signaling promotes cancer progression are poorly understood." (PMID 31208996, 2019). "Other experimental approaches targeting MDSCs in the concept of cancer include the blockade of accumulation pathways like the CCL/CCR2 axis and IL-8/CXCR1/2 interactions, which may hinder the trafficking of MDSCs to the TME and inhibit extravasation." (PMID 31847487, 2019). "Unlike commonly used cargo-carrying, vector-directed drug delivery vehicles, CCTV nanoparticles may act as therapeutics/theranostics themselves, particularly in inflammatory conditions with CCL2/CCR2 pathogenesis, including cardiovascular disease and cancer." (PMID 31723548, 2019). "Additionally, CCR2 blockade with PF-04136309 significantly inhibited metastasis development when treatment was initiated on the day of cancer cell injection." (PMID 29777108, 2018). "CCR2 antagonism has thus become an alternative method for cancer treatment." (PMID 28424406, 2017). "On the basis of CVC mainly blocking the migration of circulating monocytes to inflamed tissue via the CCL2/CCR2 axis, future studies might even address a broader range of inflammatory diseases as well as cancer." (PMID 28910354, 2017). "We postulate that CCR2 is important for Tregs migration to the cancer site." (PMID 28611777, 2017). "MDSC express chemokine receptors such as CXCR2 and CCR2 in several types of cancer." (PMID 27136535, 2016). "Blocking CCL2/CCR2 signaling pathway may serve as a novel strategy to help patients with certain kinds of cancers." (PMID 27409666, 2016). "Another study suggested that CCL2/CCR2 axis could promote cancer metastasis by up-regulation of MMP2/9 through ERK1/2 signaling pathway." (PMID 27409666, 2016). "In murine models, it has been verified that blocking CCL2/CCR2 signal pathway could restraint the infiltration of macrophages and postpone cancer metastasis." (PMID 27409666, 2016). "Of these, CCL2 together with its cognate receptor CCR2 have been shown to play key roles in cancer metastasis by sustaining cancer cell proliferation and survival, stimulating cancer cell migration and invasion, and inducing deleterious inflammation and angiogenesis." (PMID 26885690, 2016). "All these studies have demonstrated the blockage of CCR2 may have therapeutic effect in malignant tumors." (PMID 26992207, 2016). "Similarly, we showed increased expression of TAM markers such as MARCO and CCR2 in metastatic biopsies as compared to primary cancer specimens." (PMID 26418896, 2015). "CCL2 has been shown to be pivotal for immunosuppression, and the CCL2/CCR2 pathway could be a potential target for cancer therapy." (PMID 26683520, 2015). "CCL2/MCP-1 plays a key role for immunosuppression, so that inhibition of CCL2/CCR2 pathway could be a possible approach for cancer treatment." (PMID 25333973, 2014). "Our results are in contrast to those observed by others using CCL2/CCR2 targeted cancer models." (PMID 23372702, 2013). "The majority of the genes identified here, including but not limited to CCR1, CCR2, CCR3, ENA78, GPCR, GRO1, GRO2/GRO3, IP10, IL-8, NAP-2, PF-4 have been recently shown to associate with the progression of various types of cancer." (PMID 22347499, 2012). "There have been meaningful attempts at targeting the CCL2/CCR2 pathway for cancer therapy." (PMID 21943176, 2011). "Additionally, we conducted indirect coculture experiments to confirm whether inhibiting the CCL2/CCR2/PPARα axis in ADSCs affects cancer cell proliferation." (PMID 41160815, 2026). "Moreover, it has been observed that CCR2 can play a dual role in cancer." (PMID 38755605, 2024). "In recent years, extensive in vivo and in vitro studies have shown that the chemokine receptor CCR2 and its ligand system play an essential role in the pathogenesis of various acute and chronic liver diseases, including the regulation of liver homeostasis inflammation, fibrosis, and cancer." (PMID 35281057, 2022).
cancer (continued). "Thus, the CCL2/CCR2 axis has a critical role in the multiple stages of cancer metastasis." (PMID 34804061, 2021). "However, HDACi has targets other than CCR2, hence HDACi might be better than CCR2 inhibitors for cancer therapy." (PMID 33564072, 2021). "Besides, CCR2−/− cancer cells had lower surface levels of PD‐L1 compared with CCR2+/+ cancer cells." (PMID 34464477, 2021). "The expression of CCR2 could be detected in the membrane of cancer cells." (PMID 32064233, 2020). "Therefore, we combined the CR with AV in a specific nano-platform tackling cancer cells and further experiments were performed to verify by which mechanism CCR2 antagonism inhibited A549 cell proliferation in vitro, and we founded that this strategy is depended on ROS-mediated early apoptosis." (PMID 31350989, 2019). "In addition to being a potential prognostic factor for many malignancies, CCR2 might receive considerable attention as an effective marker for predicting therapeutic outcomes and is a potential target for anti-cancer therapy." (PMID 26992207, 2016). "However the role of CCL2 produced by the cancer cells appears to be confined to altering the macrophage phenotype, as cancer cells themselves were unaffected by inhibition of CCR2." (PMID 26174804, 2015). "Notably, blocking the CCL2 receptor, CCR2, has been shown to improve the therapeutic efficacy of PD-1 inhibitors in cancer treatment, suggesting that a combination of anti-PD-1/PD-L1 and CCR2-targeted therapies may provide superior outcomes compared to either treatment alone." (PMID 40940890, 2025). "CCL2, through its interaction with CCR2, facilitates cancer cell migration and recruits immunosuppressive cells into the TME, fostering cancer progression." (PMID 40568576, 2025). "High NAD(P)H autofluorescence was emitted by cancer cells and immunoactive cells including dendritic cells (CD11c+), M1 macrophages (F4/80+MCP1+CCR2+), and Th cells (CD4+)." (PMID 40112892, 2025). "Another approach is to target the cancer-cell-derived chemokine CCL2, which recruits CCR2+ inflammatory monocytes to the TME, where they become immunosuppressive MDSCs and TAMs." (PMID 40917508, 2025). "Our results provide novel insights into the intricacies of CCR2 regulation and suggest that HDAC inhibitors hold therapeutic promise for M-MDSC targeting in cancer." (PMID 39891718, 2025). "CCR2, a critical receptor of CCL2, was initially identified as a crucial receptor for cytotoxic T cell migration towards cancer cells." (PMID 40282185, 2025). "In particular, CCL2 binds to its receptor CCR2 and induces the expression of EMT-TFs Snail1 and Twist1 in cancer cells, producing morphological changes to support tumour cell migration toward SCs." (PMID 40037534, 2025). "Further research into the specific roles of CCR2 and CCL2 in different cancer types and stages of disease progression is crucial for developing effective treatments that can modulate these pathways to benefit cancer patients." (PMID 39201480, 2024). "In the present study, we report the development andvalidation of AfBPs that target the intracellular allosteric pocketof CCR2, a GPCR of interest for the development of therapies targetingautoimmune and inflammatory diseases and also cancer." (PMID 39186040, 2024). "Studies have demonstrated that in CCR2-DTR mice with pre-metastatic lungs, the inhibition of inflammatory monocyte recruitment through the CCL2-CCR2 axis resulted in a significant reduction in the expression of MMP9 and the extravasation of cancer cells." (PMID 39317708, 2024). "CCL2 produced by omental adipocytes binds to CCR2, activating the PI3K/Akt/mTOR pathway and its downstream effectors HIF-1α and VEGF-A, promoting migration and omental metastasis in cancer cells." (PMID 39408927, 2024). "Chemokines and cytokines, such as IL6/IL6R and CCR2/CCL2, serve as fundamental regulators within the TME, which has been firmly established as a pivotal driving force in cancer progression." (PMID 38468260, 2024).